LINC01220 (long independently transcribed non-coding RNA 1220)
Gene: Long non-coding RNA gene on chromosome 14 (75,294,281 to 75,306,996, forward strand). Ensembl gene ENSG00000259687.
Diseases named in the same sentence as LINC01220 in open-access papers:
LINC01220 is named in the same sentence as 3 diseases in open-access papers, as found by Europe PMC text mining. Sharing a sentence is not in itself a finding about the gene and the disease. The quoted sentences say what the papers report.
endometrial carcinoma (2 papers, 2019 to 2022). A malignant tumor arising from the epithelium that lines the cavity of the uterine body. "Interestingly, the knockdown of LINC01220 in endometrial carcinoma has been shown to inhibit proliferation and induce apoptosis, suggesting its therapeutic potential." (PMID 35565228, 2022).
cancer (1 paper, 2024). A tumor composed of atypical neoplastic, often pleomorphic cells that invade other tissues. "Others, such as LINC01220, CYTOR, LINC00910, LINC00511, PURPL, and MZF1-AS1, have been described so far only in cancer." (PMID 38616192, 2024).
tumor diseases (1 paper, 2019). "LINC01220 is located on chromosome 14q24.3 and has not been reported in tumor diseases yet." (PMID 31123170, 2019).